PIK3CA (phosphatidylinositol-4,5-bisphosphate 3-kinase catalytic subunit alpha)
Diseases named in the same sentence as PIK3CA in open-access papers (continued):
Sharing a sentence is not in itself a finding about the gene and the disease.
cancer (continued). "Three different genes, PIK3CA, PIK3CB, and PIK3CD, encode three specific p110 isoforms, p110α, β, and δ, respectively, and activating missense mutations of PIK3CA have been found as oncogenic in a variety of cancers." (PMID 30682771, 2019). "Class I PI3K isoforms are relevant for cancer, i.e., p110α (encoded by the PIK3CA gene), p110β (PIK3CB gene), p110γ (PIK3CG gene), and p110δ (PIK3CD gene)." (PMID 30832253, 2019). "This contrasts with somatic PIK3CA mutations in cancer, which are almost exclusively present in epithelial tissues." (PMID 31018529, 2019). "Discovery of PIK3CA mutations in majority of cancers has led to new targets for treatment of those cancers." (PMID 31905960, 2019). "PIK3CA mutations are commonly found in cancers such colon, breast, gastric, and brain cancers, but such mutations are rarely found in BTC and are associated with poor prognosis." (PMID 30682771, 2019). "An integrative analysis of cancer genomics using cBioPortal reported that PIK3CA, PTEN, and/or AKT1 mutations are present in over 40% of uterine, lung, breast, prostate, brain, and head and neck cancers." (PMID 31703360, 2019). "As a well-known cancer driver in many cancer types, it is expected that amplification and mutations of PIK3CA should share a common functional impact in causally regulating a common set of DEGs." (PMID 31276486, 2019). "All p110-isoforms contribute to class IA PI3Ks signaling but the p110α-encoding gene, PIK3CA, is the only isoform frequently mutated in cancer." (PMID 30999672, 2019). "Targeted therapies specific to PIK3CA-mutated cancer are seeing preliminary success in the preclinical and clinical trials." (PMID 31387972, 2019). "The PIK3CA/H1047R mutation was also reported to confer sensitivity to everolimus in early-phase clinical trials in many types of cancers." (PMID 31088410, 2019). "The present review discusses the association of mutations in the PIK3CA p110a catalytic subunit of PI3K due to the increasing reports of the altered protein product of this gene being involved in several human cancer types." (PMID 31905960, 2019). "Class IA phosphatidylinositol 3-kinase (PI3K) is activated in several cancer types by somatic activating hotspot mutations in the phosphatidylinositol-4,5-bisphosphate 3-kinase catalytic subunit alpha (PIK3CA) gene, which encodes the catalytic subunit p110α." (PMID 31036078, 2019). "The majority of cancer-associated PIK3CA mutations occur at three main hotspots in exon 9 (E542, E545) and exon 20 (H1047)." (PMID 31018529, 2019). "Missense mutations were recognized in Ncor1 and Pik3ca, oncogenes of central importance to human cancer as known driver mutations." (PMID 29925311, 2018). "PIK3CA mutations are the most common in cancer and PIK3CA is the most frequently mutated kinase in the human genome." (PMID 30001368, 2018). "Recently, numerous studies reported the presence of somatic PIK3CA-activating mutations, including those traditionally defined as “cancer-associated”, in several genetic syndromes characterized by overgrowth." (PMID 29352118, 2018). "DTCs were subjected to genome-wide copy number analysis, PIK3CA mutation screening, and gene expression analysis of 64 cancer-related genes." (PMID 30211312, 2018). "PIK3CA is one of the most commonly mutated and extensively studied oncogenes in various types of human cancer." (PMID 31093356, 2018). "One of the most prevalent genes mutated in cancer is PIK3CA which is mutated in 45% of luminal A BrCa cases." (PMID 29765551, 2018).
cancer (continued). "Here, we summarize current knowledge of PROS, evaluate challenges and strategies for disease modeling, and consider the implications of PROS as a paradigm for understanding activating PIK3CA mutations in human development and cancer." (PMID 30197175, 2018). "We found that a striking 36% (n = 14) of the associations that we identified arose between driver mutations in PIK3CA and signatures 2 or 13 across six different cancer types." (PMID 30412573, 2018). "The most frequent genetic aberrations in cancer are linked to somatic missense mutations in the gene encoding PIK3CA (p110α)." (PMID 29562629, 2018). "Although established as cancer drivers, PIK3CA hotspot mutations were also, surprisingly, identified in benign skin lesions known as epidermal nevi and seborrheic keratoses." (PMID 30197175, 2018). "Cancer cell lines or patient-derived tumors harboring PIK3CA or AKT1-E17K mutations exhibited increased sensitivity to ARQ 092 treatment." (PMID 29549527, 2018). "•More recently, cancer-associated PIK3CA mutations have also been shown to cause a wide range of clinical overgrowth disorders, many with different syndromic names based on the pattern of overgrowth." (PMID 30197175, 2018). "In the TCGA analysis, PIK3CA mutations were more dispersed in EBV-positive cancers, but localized in the kinase domain (exon 20) in EBV-negative cancers." (PMID 30008616, 2018). "Since the observation of high mutational frequency in human cancers suggests PIK3CA as a driver, much research effort has focused on this gene." (PMID 30544563, 2018). "Preclinical data also suggested that PIK3CA mutation makes cancer cells more vulnerable to PI3K inhibition by alpelisib." (PMID 31093356, 2018). "In CM/ESCC group, we observed that the presence of PIK3CA mutations was significantly associated with a lower survival rate from the diagnosis of cancer compared to wild-type patients." (PMID 30619505, 2018). "Mutation of PIK3CA leads to increased enzymatic activity of p110a and Akt signaling activation, lead to suppressed cellular apoptosis and enhanced cancer invasion." (PMID 29970892, 2018). "Cumulative evidence indicated a high frequency of mutations in the PIK3CA gene, which codes for p110α in various human cancers." (PMID 30034618, 2018). "The obvious implication of activated PIK3CA in cancer lead to numerous studies concerning the impact of PIK3CA mutations in prognosis and therapy outcome." (PMID 30001368, 2018). "Hyperactivation of phosphatidylinositol 3-kinase (PI3K) signaling cascades is one of the most common events in human cancers, often via PIK3CA hotspot missense mutations." (PMID 29515801, 2018). "For example, mutations in PIK3CA are well-described in many cancers, yet the Cancer Hallmark Network Framework30 analysis succeeded to identify a feed-forward loop of genes controlling PIK3CA activity and associated with worsened prognosis." (PMID 29743726, 2018). "Neuroectodermal and mesodermal cancers show very low occurrence, if any, of activating PIK3CA mutations." (PMID 30197175, 2018). "We demonstrate here that PIK3CA mutation was a significant prognostic factor for poor OS and cancer-specific survival (CSS) after CCRT." (PMID 30075505, 2018). "Patients with wild-type PIK3CA showed significantly improved cancer-specific survival as compared with mutated patients (P = .044)." (PMID 30075505, 2018). "PIK3CA mutation has been observed in various solid tumors and plays a crucial and intricate role in carcinogenesis and the development of malignant tumors." (PMID 30547809, 2018). "Cancer-associated activating PIK3CA mutations, when occurring in isolation during early development, cause a spectrum of rare disorders characterized by asymmetric, and often severe, excessive tissue growth and malformations." (PMID 30197175, 2018).
cancer (continued). "In particular, we associated PIK3CA activating mutations with altered activities of distinct sets of TFs in different cancers." (PMID 28139702, 2017). "Even though PIK3CA was the most mutated genes in multiple cancers, there was few studies reporting the drug sensitivity or outcomes when the mutation was presented." (PMID 29228676, 2017). "The association of APOBEC polymorphisms with cancer risk and the apparent APOBEC-induction of PIK3CA mutations indicate that these enzymes likely play significant roles in promoting cancer onset." (PMID 28117753, 2017). "The gene encoding the p110α subunit, PIK3CA, is mutated at a rate of nearly 30% in human cancers, including colorectal cancer, glioblastoma, and gastric cancer." (PMID 29109464, 2017). "Activating PIK3CA mutations present novel therapeutic targets, and clinical trials of targeted inhibitors are underway in human cancers." (PMID 29190660, 2017). "Further investigations into the precise molecular mechanisms associated with aspirin treatment of cancers with mutant PIK3CA are warranted." (PMID 29152088, 2017). "One strategy is to use a detection method with a higher sensitivity, thereby reducing the risk of missing a relatively small fraction of cancer cells carrying a PIK3CA mutation." (PMID 28068934, 2017). "A recent study on cell lines has demonstrated that the presence of PIK3CA mutations can sensitize cancer cells to mTOR inhibitor, everolimus." (PMID 28392480, 2017). "Somatic mutations clustered in PIK3CA hotspot regions are frequently found in a wide array of cancers and their oncogenic potential is well documented in functional studies." (PMID 29088297, 2017). "Malignancies are rare in the PROS spectrum, even if PIK3CA is the most common mutated gene in cancer." (PMID 28353628, 2017). "One of these mutations, PIK3CA p.E545K, is a recurrent somatic mutation detected across many cancer types." (PMID 28492226, 2017). "Our analysis predicts distinct dysregulated transcriptional regulators downstream of somatic alterations in different cancers, and we validate the context-specific differential activity of TFs associated to mutant PIK3CA in isogenic cancer cell line models." (PMID 28139702, 2017). "Only ELK1, a TF downstream of the MAPK/ERK pathway, is dysregulated by PIK3CA or PTEN mutations in all three cancers." (PMID 28139702, 2017). "Cancer driver gene mutations (e.g., PIK3CA, HRAS) were identified in only a minority of tumors, and the average mutational load was low at 0.5/MB." (PMID 29084941, 2017). "Several studies have provided evidence to suggest that cancer cells harboring PIK3CA gain-of-function mutations are selectively sensitive to inhibitors of various components of the PI3K pathway." (PMID 28423515, 2017). "The frequency of mutations indicates that PIK3CA is one of the most highly mutated oncogenes in human cancers." (PMID 28353628, 2017). "PIK3CA mutations are commonly found in a variety of cancers, with a prevalence of about 2% to 4% in NSCLC." (PMID 28212572, 2017). "In HNSCC, PIK3CA mutations tend to be heavily focused on the helicase (exon 9) and kinase (exon 20) domains, which also holds true for PIK3CA mutations in most sporadic cancers." (PMID 28108737, 2017). "Emerging evidence suggests that PIK3CA mutations can occur late in the evolution of some cancers, being present in only a subset of cancer cells within the tumour." (PMID 29170395, 2017). "NIH3T3-METM1268T cells were subsequently transfected with vectors containing the two commonest PIK3CA mutations encountered in human cancer: PIK3CAE545K (helical domain) and PIK3CAH1047R (kinase domain)." (PMID 28532501, 2017). "PIK3CA is frequently mutated in several cancer types, including breast, colorectal, endometrial, ovarian and skin tumors." (PMID 28353628, 2017).
cancer (continued). "Activating mutations of PIK3CA, a common characteristic of many cancer types, including lung SCC and head and neck SCC (HNSCC), have been reported but do not appear to occur at high frequency in cSCC." (PMID 28696382, 2017). "For instance, PIK3CA is the most well-studied oncogene among our 3q gene signature due to its high mutation rate in human cancer, especially in breast cancer." (PMID 28387221, 2017). "These previously unappreciated roles of PIK3CA mutation show that PI3K signalling can contribute to the generation of irreversible genomic changes in cancer." (PMID 29170395, 2017). "The strong survival benefit in patients with a PIK3CA mutation can only partly explain the effect of aspirin found in the general cancer population." (PMID 28125730, 2017). "BYL719 is an α-specific PI3K inhibitor and entered into clinical trials in 2010 to assess the therapeutic potential for treating cancers in which the PIK3CA gene is mutated or amplified." (PMID 28806782, 2017). "Remarkably, we did not observe a significant survival association with other well-known cancer genes, such as PIK3CA (lowest p = 0.007, q = 0.5 in UCEC), BRAF (lowest p = 0.028, q = 0.98 in KIRP), and FBXW7 (lowest p = 0.018, q = 0.99 in MELA-AU)." (PMID 28240231, 2017). "Such cancer type–specific associations were also seen for PIK3CA, KRAS, GATA3, CTCF, CDH1, and ARIDA1." (PMID 29125844, 2017). "PIK3CA somatic mutations are frequently present in various human cancers such as liver, breast, colon, ovary, and GC." (PMID 29207615, 2017). "Even if there are not any clinical trials to evaluate PI3K p110α inhibitors in PROS, pre-clinical studies in both PROS and cancers bearing PIK3CA mutations have yielded promising results." (PMID 28353628, 2017). "Oncogenicity of the p110α isoform is well established and mutations of PIK3CA play a causative role in the development of many cancer types (reviewed by Samuels)." (PMID 28420128, 2017). "PIK3CA mutations frequently occur in many human cancer types, and have been established as causative and key driver of cancer." (PMID 28894288, 2017). "A similar analysis of a broad variety of therapy-naïve cancers using a PCR-based mass spectrometry assay found that PIK3CA mutations are often associated with other driver mutations." (PMID 27304188, 2016). "A large body of evidence points to similar as well as distinct effects of Pten loss versus PIK3CA mutations on cancer progression and response to therapy." (PMID 26814435, 2016). "But more significantly, our study has discovered that gene mutation and gene amplification in two cancer driver genes, PIK3CA and GATA3, are correlated oppositely to the IDC histologic changes." (PMID 27283966, 2016). "PI3Kα (PIK3CA) is a mostly studied subtype, whose mutations or abnormal expression are most commonly reported in different cancers." (PMID 27494891, 2016). "Reasons for this inconsistency include varying effects of PIK3CA mutation in different cancer types and the fact that PIK3CA mutations can co-occur with molecular events that modulate PIK3CA mutational effects." (PMID 27589846, 2016). "PI3K-AKT-mTOR signalling is known to play a role in carcinogenesis and tumour progression, and mutations have been reported in PIK3CA in a range of human cancers." (PMID 27765909, 2016). "The frequency of point mutations in CHGs is very low when compared with typical cancer gene drivers, such as ‘phosphatidylinositol‐4,5‐bisphosphate 3‐kinase, catalytic subunit alpha’ (PIK3CA)." (PMID 27516958, 2016).
cancer (continued). "Screening of a panel of cancer cell lines has revealed the hypersensitivity of cells with PIK3CA mutations to the α-specific inhibitor BYL719." (PMID 27048245, 2016). "Cancer cells in MPE had coexisting acquired PIK3CA c.1633G > A (p.E545K) mutation and EGFR c.2369C > T (p.T790M), in addition to EGFR c.2573T > G (p.L858R)." (PMID 27734950, 2016). "In particular evidence on PIK3CA, other mutations and other possible markers should be collected as a matter of urgency in cancers of breast, prostate and other organs." (PMID 27096951, 2016). "PIK3CA functions as an oncogene, and activating (or gain-of-function) mutations of PIK3CA are widely seen in human cancers." (PMID 27631024, 2016). "More than 30 % of various human cancer types were found to contain mutations in the PIK3CA gene, and it is frequently mutated in cancers of the liver, breast, stomach, breast, lung, and colon." (PMID 27405731, 2016). "The gene encoding PI3Kα (PIK3CA) is often mutationally activated in cancers, which supports its role as a cancer driver." (PMID 27096871, 2016). "In contrast, MSI cases generally lacked targetable amplifications, and mutations in ERBB1-3 and PIK3CA were noted, with many mutations at “hotspot” sites observed in other types of cancers." (PMID 27233623, 2016). "Recent studies have reported high frequencies of somatic mutations in the PI3K catalytic subunit, p110α gene (PIK3CA), in various cancer types including HNSCC." (PMID 27119232, 2016). "PIK3CA mutations appear at early stages in cancer progression, whereas PTEN inactivation is a later event." (PMID 27863432, 2016). "Single amino acid substitution: E542K, E545K, or H1047R was responsible for 80% of the cancer-specific mutations in PIK3CA." (PMID 27564098, 2016). "Application of sensitive genomic techniques has revealed that the affected tissues in these individuals often contain post-zygotic mosaic somatic alterations that are identical to those observed in cancer, such as PIK3CA hotspot mutations." (PMID 27716394, 2016). "Previous studies have shown that activating mutations in PIK3CA promote invasion of human cancer cells and that cells expressing PIK3CA-E545K migrate faster in cell-based assays." (PMID 27489350, 2016). "The most common PIK3CA mutations are p.Glu542Lys, p.Glu545Lys, and p.His1047Arg, which are seen in ~80% of somatic tissues in cancer (and therefore termed “hotspot” mutations)." (PMID 27631024, 2016). "Previous studies evaluating the association between PIK3CA mutations and prognosis in human cancers have yielded variable results." (PMID 27388016, 2016). "Mutations in the PIK3CA gene, which codes for the p110alpha isoform are noted in a number of cancers." (PMID 27655636, 2016). "The gene encoding phosphatidylinositol 3-kinase catalytic subunit α-isoform (PIK3CA, p110α) is frequently activated by mutation in human cancers." (PMID 27797363, 2016). "Numerous evidences have associated activating PIK3CA mutations with a more tumorigenic phenotype; however, contradicting results have been obtained when evaluating the prognostic significance of PIK3CA mutations in different human cancers." (PMID 27119232, 2016). "Recent large-scale sequencing of human cancer genomes reveals that PIK3CA is the most frequently mutated oncogene in human cancer." (PMID 27321283, 2016). "HCT-116 cancer cells are characterized by a constitutive activation of the PI3K/Akt signaling pathway through activating mutations in PIK3CA." (PMID 27102434, 2016). "HPV-related cancers were characterized by mutation of the PIK3CA gene, novel alterations involving loss of TRAF3 function, and amplification of the cell cycle gene E2F1." (PMID 27776338, 2016). "A PIK3CA mutation is a well-known genetic aberration identified across many types of cancer, including breast cancer." (PMID 27283966, 2016). "Accordingly, α-specific PI3K inhibitors like BYL719 have shown promising preclinical and clinical results with cancers harboring mutated and/or amplified PIK3CA." (PMID 27048245, 2016).